IL2 (interleukin 2)
Diseases named in the same sentence as IL2 in open-access papers (continued):
Sharing a sentence is not in itself a finding about the gene and the disease.
melanoma (continued). "To date, two cytokines have achieved FDA approval as single agents for cancer treatment: high-dose, bolus IL-2 for metastatic melanoma and renal cell carcinoma and IFN-α for the adjuvant therapy of Stage III melanoma." (PMID 24213115, 2011). "In our study, we have analysed TIL characteristics from 17 melanoma patients, whereof five have undergone lymphodepletion and TIL-based ACT with low-dose IL-2." (PMID 21773037, 2011). "There has been intense interest in the discovery of predictive biomarkers for better selection of patients likely to respond to IL-2 therapy for both RCC and melanoma." (PMID 24213115, 2011). "Hu14.18-IL2 combines an antibody against the disialoganglioside GD2, a carbohydrate antigen found on melanomas, neuroblastomas and some sarcomas, with IL-2." (PMID 24212958, 2011). "We previously found that administration of an interleukin 2/diphtheria toxin conjugate (DAB/IL2; Denileukin Diftitox; ONTAK) to stage IV melanoma patients depleted CD4+CD25HIFoxp3+ regulatory T cells and expanded melanoma-specific CD8+ T cells." (PMID 22165955, 2011). "In response to autologous melanoma cell line, this clone is lytic and produced in decreasing order the following Th1 and Th2 cytokines: IL-13, IL-4, TNF-α, GM-CSF, IL-2, IFN-γ and IL-5." (PMID 20052413, 2010). "Accordingly, a low-dose IL-2 regimen diminishes the magnitude and frequency of CTL responses to a peptide vaccine against melanoma." (PMID 21059266, 2010). "Despite decades of evaluating new therapeutic modalities for advanced melanoma, patients are mainly being treated with agents that display low response rates, i.e. DTIC and IL-2." (PMID 20128926, 2010). "We have shown earlier that the combination of IL-2 and CD40L had an improved efficacy over the use of single agents, when applied for direct in situ therapy or vaccination therapy in a mouse melanoma model." (PMID 20670430, 2010). "Novel melanoma-targeted therapeutic agents are needed to improve prognosis, since traditional treatments such as dacarbazine (DTIC) and IL-2 only yield a 5% survival advantage of more than five years for patients with advanced melanoma." (PMID 20128926, 2010). "When using TETP as cancer cell-selective promoter to restrict IL-2 and CD40L transgene expression to melanoma cells, tight expression was demonstrated, which was only 5 to 40-fold lower than those from vectors controlled by the nonselective CMV promoter." (PMID 20670430, 2010). "HemoHIM administration significantly enhanced IL-2 (p < 0.001) and IFN-γ (p < 0.05) production in melanoma-bearing mice treated with cisplatin." (PMID 19292900, 2009). "In our data, HemoHIM administration with cisplatin injection increased the secretion of IL-2 and IFN-γ in melanoma-bearing mice." (PMID 19292900, 2009). "Clinical studies were performed with peripheral blood NK cells from haploidentical donors that were activated ex vivo with IL-2 overnight in AML, melanoma and RCC patients." (PMID 19440333, 2009). "DAB/IL2 administration transiently decreased CD4+CD25-, CD4+CD25+, CD4+CD25HIFoxp3-, CD4+CD25HIFoxp3+, CD8+ T cells and, in certain patients, melanoma antigen-specific CD8+ T cells." (PMID 18334033, 2008). "rIFN-α, interleukin 2 [IL-2], and IFN-γ1b) and provided some treatment effects against metastatic renal tumors and melanoma." (PMID 16603073, 2006). "Here we compare the potential therapeutic benefit of transduction with IL-2 or IL-4 alone, and combined IL-2 + IL-4 in B16F10 cells, a murine malignant melanoma of poor immunogenicity." (PMID 8679459, 1996). "Interleukin 2 (IL-2) immunotherapy has met with limited success in the treatment of renal cell carcinoma (RCC) and malignant melanoma (MM)." (PMID 7640231, 1995). "Twelve patients undergoing IL-2 and flavone acetic acid (FAA) combination immunotherapy for advanced melanoma were studied throughout treatment for the induction of measurable levels of bioactive TNF, GM-CSF and IL-6 in their serum." (PMID 8512819, 1993).
melanoma (continued). "The clinical and immune modulatory effects of interleukin-2 (IL-2) and interferon (INF) alfa-2a were examined in a phase II study in patients with metastatic renal cell carcinoma (six patients) and melanoma (eight patients)." (PMID 1997108, 1991). "This retrospective study compared the efficacy and safety of intralesional T-VEC and IL-2 in patients with non-resectable stage III melanoma." (PMID 40171522, 2025). "We also analyzed samples from dogs in a third trial, the University of Wisconsin (UW) cohort, where dogs with melanoma were treated with low-dose molecular targeted radionuclide therapy (MTRT), external beam radiation therapy (EBRT) and intratumoral injection of GD2/IL-2 fusion immunocytokine." (PMID 41208961, 2025). "This retrospective study aimed to compare the efficacy and safety of intralesional T-VEC and IL-2 in non-resectable stage III patients with melanoma treated at a single center between January 2016 and September 2024." (PMID 40171522, 2025). "Unlike STS patients, melanoma patients exhibited a significant increase in serum IL-2 by D14, which then reverted to baseline by D28." (PMID 40386779, 2025). "Of these therapies, the most widely studied is the use of in vivo γδ T cells activated with zoledronate and/or IL-2, with or without letrozole as an adjunct, for use in prostate, renal cell, and breast cancers, as well as melanoma and neuroblastoma." (PMID 40148988, 2025). "Pretreatment with MAC-3-190 alone did not significantly increase the IL-2+ T cell count compared with the control T cells after coincubation with melanoma cells." (PMID 40574005, 2025). "IL2-tethered small EVs (IL2-sEVs) derived from engineered Jurkat T cells have been shown to enhance CD8+ T cell anticancer activity and reduce PD-L1 expression in melanoma cells, thereby reshaping the immunosuppressive tumor microenvironment." (PMID 41511353, 2025). "Moreover, IL2-tethered small EVs (IL2-sEVs) derived from engineered Jurkat T cells enhanced CD8+ T cell anticancer activity and reduced PD-L1 expression in melanoma cells via specific microRNAs, demonstrating their potential as cancer immunotherapeutic agents." (PMID 40317075, 2025). "Additionally, RT-PCR analysis showed that Jurkat cells co-cultured with Vin-treated melanoma cells exhibited significantly higher mRNA levels of IFNγ, GZMB, IL-2, and TNFα in the activated state." (PMID 40866941, 2025). "Successful performance of TIL therapy in patients with advanced melanoma and concomitant CLL/SLL may be challenging due to the potential contamination of the harvested tumor sample with SLL and IL-2-induced ex vivo modulation of atypical B lymphocytes." (PMID 41333460, 2025). "Ex vivo studies demonstrated that co-culturing human PBMCs with melanoma cells inhibited T cell activation, decreasing IL-2-secreting T cells both in the presence and absence of IFN-γ." (PMID 40574005, 2025). "This in vivo finding, unfortunately, did not match the findings of a clinical trial conducted on 24 melanoma patients who received different concentrations of CAR-T cells combined with administration of low or high dose of IL-2." (PMID 39086722, 2024). "Our results show that the addition of IL-2 and IL-12 enables more potent responses to RT and checkpoint blockade for moderately immunogenic MC38 and CT26 colon adenocarcinomas, relatively cold B78 melanoma, and very cold 9464D-GD2 neuroblastoma." (PMID 39076988, 2024). "Disappointing results from the late-stage clinical trial of BEMPEG, a non-alpha IL-2, in combination with NIVO for advanced melanoma, has prompted a reassessment of IL-2 biology and engineering strategies." (PMID 39114660, 2024). "Lifileucel, a heterogeneous TIL therapy, was given as a one-time infusion along with a median 5.5 infusions of IL-2 after a lymphodepleting regimen of cyclophosphamide and fludarabine to patients with stage III or IV melanoma who were unresponsive to both ICI therapy and targeted therapy." (PMID 39682188, 2024).
melanoma (continued). "As IL-2 could promote the proliferation and activation of NK cells, the absolute amount of NK cells (CD3−NK1.1+) in murine melanoma tumors (B16-F10 cells) after treatment with NRP+I was 1.6 and 1.5 times higher than PTX + IL-2 and NRI groups, respectively." (PMID 39065636, 2024). "Though IL-2 treatment could induce durable response in melanoma and RCC patients, the short half-life of IL-2 requires a therapeutic schedule with an 8-h interval." (PMID 38520006, 2024). "Interleukin-2 (Aldesleukin) has been licensed by the Food and Drug Administration (FDA) for the treatment of individuals with advanced forms of renal cell carcinoma (metastatic RCC) and melanoma." (PMID 38166628, 2024). "Adoptively transferred gp-100 TCR T cells conjugated to these NPs expanded more, demonstrating higher activity and better tumor control in a murine B16F10 melanoma metastasis model, with even lower toxicity, when compared to ACT combined with systemically administered IL-2." (PMID 39030582, 2024). "In addition, recombinant IL-2 has been approved by the FDA for the treatment of metastatic RCC and melanoma." (PMID 37332770, 2023). "The remission rate in melanoma patients who had never received IL-2 previously reached 60% (nine out of 15 patients) compared to the 40% who had earlier received IL-2 (two out of five patients)." (PMID 37444586, 2023). "The expression of all three transgenes was demonstrated in LOAd732-infected melanoma cell lines and DCs and the addition of the IL-2 transgene did not impair the oncolytic function of the virus compared to LOAd703 expressing only TMZ-CD40L and 4-1BBL." (PMID 37501121, 2023). "Overall, in comparison to healthy controls, melanoma patients demonstrated reduced numbers of CD4 and CD8 naive T cells coupled with indications of memory T‐cell activation denoted by increased Ki67 and IL‐2 positivity and a skewed γδT‐cell phenotype." (PMID 37692904, 2023). "In addition to IL-2, other cytokines have also been used in cancer treatment, such as INF-α in the treatment of chronic granulocytic leukemia, malignant melanoma, and renal cell carcinoma." (PMID 37305384, 2023). "Currently, common therapies for melanoma include targeted inhibitors of BRAFV600E and MEK kinases in the mitogen activated protein kinase (MAPK) pathway, interleukin-2 (IL-2), oncolytic viruses, interferon, and emerging immune checkpoint inhibitors (ICI) alone or in combination." (PMID 37833287, 2023). "Additionally, high-dose recombinant IL-2 has been approved by the Food Drug Administration (FDA) for the treatment of metastatic renal cell carcinoma (RCC) and melanoma." (PMID 37332770, 2023). "Therefore, we proceeded with the co-administration of IL-2 and CU06-1004 from day 7 after injecting the B16F10 melanoma tumor into the mice." (PMID 37711172, 2023). "While serum TNF-α and IFN-γ levels did not change, IL-2 levels were upregulated similarly to those seen in melanoma tissues on the fourth and seventh days after treatment with Ce6-PDT." (PMID 36835310, 2023). "Hu14.18-IL-2 is an immunocytokine (IC) fusion protein consisting of a humanized anti-disialoganglioside (GD2) monoclonal antibody and human recombinant IL-2 (hrIL-2) developed to exert superior anti-tumor activity against melanoma and neuroblastoma." (PMID 36936961, 2023). "High-dose interleukin-2 (IL-2), a potent inducer of cytotoxic T-cells and NK cells, was one of the first FDA-approved immunotherapy drugs in advanced cancer, with a role in the treatment of melanoma and renal cell carcinoma." (PMID 36900202, 2023). "Accordingly, higher sCD8 levels were favorable in melanoma and renal cell carcinoma patients but only during treatment with IL-2 and not with IFN-γ." (PMID 36688998, 2023).
melanoma (continued). "In the mouse model of melanoma, WKYMVm can act on FPRs, reduce the number of myeloid-derived suppressor cells (MDSCs) in tumor tissues, upregulate IL-2 and IFN-γ, promote NK cell migration and increase NK cells infiltration by activating ERK, thereby inhibiting the growth of melanoma cells." (PMID 36120322, 2022). "High-dose IL-2 therapy increased the expansion of the ICOS+ Treg population, which may predict clinical outcomes in melanoma." (PMID 35585567, 2022). "Accordingly, targeting Tregs via CD25-antibody (Daclizumab) or by a DTx-IL2-fusion protein (ONTAK) did not benefit melanoma patients due to effector cell elimination." (PMID 34584204, 2022). "Another fusion antibody, L19-IL-2, targeting the EDB domain of FN combined with the IL2, was effective in an animal model and achieved stable condition in a clinical trial including patients with melanoma and renal cell carcinoma." (PMID 35558554, 2022). "Thus far in pre-clinical studies, IL-2/NARA1 and NARA1leukin complexes induced antitumor immunity as a monotherapy and in combination with mouse melanoma gp100 vaccines." (PMID 35651800, 2022). "Clinically, i.t. administration of wild-type IL-2—not as an immunocytokine—yielded impressive improvement in therapeutic efficacy against melanoma lesions and reduced toxicity." (PMID 36712341, 2022). "Upon IL-2, IL-12, and IL-18 stimulation, Vδ2 T cells also induced cell cycle arrest in various tumor cells like bladder carcinoma (T24), breast cancer (MCF7) and melanoma (WM115)." (PMID 36429001, 2022). "Identification of key melanoma genetic drivers led to the development of pharmacological BRAFV600E and MEK inhibitors, significantly improving metastatic patient outcomes over traditional cytotoxic chemotherapy or pioneering IFN-α and IL-2 immune therapies." (PMID 36497341, 2022). "Traditional immunotherapy for metastatic melanoma is mainly divided into the following five categories: cytokines such as interleukin 2 (IL-2) and α interferon (IFN-α), tumor vaccine based on melanoma antigen or DC, oncolytic virus, T cell adoptive therapy and immune checkpoint inhibitors (ICIs)." (PMID 36466338, 2022). "In advanced melanoma patients, PD-1 is upregulated transiently and often sequentially by neoantigen-specific CD8+ T cells upon T-cell activation and exposure to common gamma-chain cytokines including IL-2 in vitro." (PMID 35480107, 2022). "Another trial with positive results in stage IV melanoma patients used a hapten modified vaccine, MVax (a vaccine prepared form the patients’ own cancer cells mixed with BCG and used in combination with cyclophosphamide followed by IL-2)." (PMID 36358601, 2022). "More than 10 different drug types have been approved by the FDA for the treatment of melanoma, including dacarbazine chemotherapy, BRAF and MEK-targeted therapy, recombinant interferon alpha-2b and IL-2, immune checkpoint inhibitors (ICIs), and oncolytic viral therapy (T-VEC)." (PMID 35495634, 2022). "Their introduction to therapy has reduced the role that chemotherapy and non-specific active immunotherapy (interferon, interleukin 2) plays in the treatment of patients with advanced melanoma." (PMID 35406444, 2022). "For example, ISV applying ipilimumab (just 2 mg once a week for 8 weeks) and interleukin-2 (IL-2) generated responses in both injected and noninjected lesions, with minimal additional toxicity in advanced melanoma." (PMID 36139425, 2022). "To extend this to an in vivo model of adoptive transfer immunotherapy, we next expanded purified TCR-transgenic GP100-reactive CD8+ T cells in IL-2, IL-15, or OMCPmutIL-2 for 2 weeks and adoptively transferred them to C57BL/6 mice bearing established B16 melanoma." (PMID 35603788, 2022). "For this purpose, several approaches, with different viral vectors, were used to express cytokines such as IL-2, IL-12, IL-15, IFN-γ, IFN-β, reinforces the potential of combining OV and cytokines for immunotherapy for melanomas." (PMID 35495634, 2022).
melanoma (continued). "Since the first approval for the treatment of hairy cell leukemia, IFN-α has also been approved for the treatment of melanoma, follicular non-Hodgkin’s lymphoma, AIDS-related Kaposi’s sarcoma and renal cell carcinoma, while IL-2 was approved for the treatment of renal cell carcinoma and melanoma." (PMID 34579759, 2021). "Furthermore, clinical studies have demonstrated that in vivo expansion of Tregs can occur when treating patients either with low-dose IL-2, e.g., after HSCT, or when using high IL-2 doses as was shown in melanoma patients." (PMID 34066067, 2021). "The field of ACT for melanoma took flight in 1987, when an objective response rate of 34% was achieved with the use of TILs in combination with high dose IL-2 with or without cyclophosphamide." (PMID 34572949, 2021). "When mEHT was combined with either primary human NK cells or the IL-2 independent NK-92MI cell line injected subcutaneously, the accumulation of NK cells was observed at the mEHT pretreated melanoma nodules but not at the untreated controls." (PMID 33732640, 2021). "Patients with advanced unresectable melanoma may receive high-dose interleukin-2 monotherapy approved by FDA in 2011, meanwhile, the PEGylated interferon-α2b could be used as an adjuvant treatment for surgically treated melanoma patients." (PMID 33777924, 2021). "NCT03970382 is a study of gene-edited autologous neoantigen-targeted TCR T cells with or without anti-PD-1 ICI or IL-2 in patients with a range of solid tumours including melanoma." (PMID 36284898, 2021). "While these therapies are used infrequently in melanoma in favor of current ICI immunotherapy, a small number of patients do well, and may have been cured with IL-2 in metastatic RCC." (PMID 33732652, 2021). "Another melanoma trial, not yet recruiting, will compare response rates between patients receiving intralesional IL-2 alone and patients receiving intralesional IL-2 and intralesional BCG (NCT03928275)." (PMID 34055652, 2021). "On the other hand, no survival benefits were observed after administration of IL2 in metastatic renal cancer and melanoma, although the cytokine had led to a regression of metastatic tumors." (PMID 33690729, 2021). "It was demonstrated in a mouse model of melanoma that this delivery system had better efficiency than free IL-2, without evident toxicity." (PMID 33546290, 2021). "Nowhere is this better characterized than in melanoma where the majority of patients have T cell responses to shared melanoma antigens that can be detected in tumor-infiltrating lymphocytes (TIL) following activation and expansion in IL-2." (PMID 34301276, 2021). "Jespersen and colleagues studied melanoma in an autologous PDX model where tumor cells and TILs from the same patient were implanted into NOG/NSG mice and T cell survival was maintained with continuous presence of IL-2." (PMID 32570871, 2020). "Prior to 2011, the only FDA-approved melanoma therapies were dacarbazine and high dose interleukin-2, yet both do not improve the median overall survival of melanoma patients." (PMID 33378390, 2020). "Moreover, the genetic deletion of CISH, in a mouse model of melanoma, significantly increases CD8+ T cells related cytokines production (IFNγ, TNFα, and IL-2) and anti-tumor reactivity, improving the survival of mice for more than 60 days." (PMID 33287413, 2020). "There were no long-lasting toxicities from IL-2 with the exception of hypothyroidism requiring levothyroxine in 16 patients and vitiligo in 6 patients, all of whom had regression of melanoma during treatment." (PMID 32467299, 2020). "The overall survival at 1, 3 and 5 years after CPI or BRAF-targeted therapy independent of IL-2 immunotherapy in patients with advanced melanoma is significant, yet the reality for the majority of patients is that multiple lines of systemic therapy are needed." (PMID 32467299, 2020).